RN7SL296P (RNA, 7SL, cytoplasmic 296, pseudogene)
Gene: Miscellaneous RNA gene on chromosome 3 (33,103,008 to 33,103,306, forward strand). Ensembl gene ENSG00000275090.
Homologues: Orthologues: macaque Metazoa_SRP (96% identical). Paralogues in human: RN7SL1 (88% identical), RN7SL2 (87% identical), RN7SL3 (87% identical), RN7SL357P (84% identical), RN7SL14P (84% identical), RN7SL566P (84% identical), RN7SL478P (83% identical), RN7SL507P (83% identical), RN7SL664P (83% identical), RN7SL44P (83% identical), RN7SL63P (83% identical), RN7SL660P (83% identical), and 704 more.